CARNMT1 (carnosine N-methyltransferase 1)
Description:
Protein-histidine N-methyltransferase that specifically catalyzes the N1-methylation (pros-methylation) of histidine residues in a wide range of proteins. It primarily monomethylates proteins containing RNA-binding C3H1 zinc finger motifs, such as U2AF1, ZC3H15, ZC3H18, PPP1R10, PRR3 and RNF113A, thereby modulating mRNA splicing and turnover. Additionally, methylates the dipeptide carnosine (beta-alanyl-L-histidine) at the N1 position to generate anserine, an abundant component of vertebrate skeletal muscle. Acts also on other L-histidine-containing di- and tripeptides, such as Gly-Gly-His, Gly-His, and homocarnosine (GABA-His).
Synonyms: C9orf41; FLJ25795; UPF0586
Tractability: Small molecule: a structure with a bound ligand is known. PROTAC: ubiquitination databases record sites on it.
Gene: Protein-coding gene on chromosome 9 (74,980,790 to 75,028,437, reverse strand). Ensembl gene ENSG00000156017.
Subcellular location: Cytoplasm, cytosol; Nucleus
Pathways (Reactome):
Metabolism: Histidine catabolism
Gene Ontology:
Molecular function: carnosine N-methyltransferase activity; protein binding; protein homodimerization activity; protein-L-histidine N-pros-methyltransferase activity; S-adenosylmethionine-dependent methyltransferase activity
Biological process: carnosine metabolic process; L-histidine catabolic process
Cellular component: cytosol; nucleus
Genetic constraint (gnomAD): Loss-of-function variants: 21 observed, 26.13 expected, observed/expected ratio (o/e) 0.8, 90% interval 0.57 to 1.16. The upper end of that interval is the gene's LOEUF score, 1.16, which puts it in group 5 of 6, group 1 being the genes least tolerant of losing a copy. Missense variants: 349 observed, 365.05 expected, observed/expected ratio (o/e) 0.96, 90% interval 0.88 to 1.04. Synonymous variants: 133 observed, 123.64 expected, observed/expected ratio (o/e) 1.08, 90% interval 0.93 to 1.24.
Homologues: Orthologues: chimpanzee CARNMT1 (100% identical), dog CARNMT1 (97% identical), pig CARNMT1 (97% identical), rabbit CARNMT1 (96% identical), guinea pig CARNMT1 (93% identical), macaque CARNMT1 (92% identical), mouse Carnmt1 (90% identical), rat Carnmt1 (90% identical), tropical clawed frog nmrk1 (71% identical), zebrafish carnmt1 (49% identical), Drosophila melanogaster CG11596 (41% identical), Caenorhabditis elegans Y48E1C.2 (37% identical).
Diseases named in the same sentence as CARNMT1 in open-access papers:
CARNMT1 is named in the same sentence as 1 disease in open-access papers, as found by Europe PMC text mining. Sharing a sentence is not in itself a finding about the gene and the disease. The quoted sentences say what the papers report.
cancer (2 papers, 2023 to 2025). A tumor composed of atypical neoplastic, often pleomorphic cells that invade other tissues. "Thus, U2AF1 in the CARNMT1 KO cells behaves similarly to the U2AF1 S34F/Y mutants, raising a fascinating question: Do these cancer-associated mutations mimic a cell state in which CARNMT1 activity is physiologically down-regulated to execute a specific splicing program?" (PMID 37673460, 2023).